BDNF (brain derived neurotrophic factor)
Diseases named in the same sentence as BDNF in open-access papers (continued):
Sharing a sentence is not in itself a finding about the gene and the disease.
mood disorder (continued). "Another possible reason for the failure to demonstrate an association between BDNF and mood disorders is that in most mouse models BDNF or TrkB are manipulated in most or all brain areas." (PMID 24817844, 2014). "Patients carrying one or two BDNF minor alleles (GA or AA genotypes) showed a nominally significant association with healthy controls, implying a protective effect of this allele for mood disorder." (PMID 24944871, 2014). "Met variants are accompanied by decreased BDNF distribution in the dendrites and impairment in regulated secretion, and are considered to be “vulnerability” alleles in mood disorders." (PMID 25202283, 2014). "Brain-derived neurotrophic factor (BDNF) and its receptor neurotrophic tyrosine kinase receptor type 2 (TrkB) have been implicated in mood disorders." (PMID 24058344, 2013). "The striatal BDNF/TrkB system is thereby implicated in many physiologic and pathophysiologic processes, the latter including mood disorders, addiction, and Huntington’s disease." (PMID 24369067, 2013). "Changes in brain derived neurotrophic factor (BDNF) expression have been associated with mood disorders and cognitive dysfunction." (PMID 22265241, 2012). "Longitudinal designs may help clarify causal relationships between BDNF, serotonin, and mood disorder development or progression." (PMID 39493096, 2024). "Furthermore, the review discusses the interplay between BDNF and stress-related mood disorders, shedding light on the mechanisms underlying AN vulnerability to stress events." (PMID 39203753, 2024). "Moreover, the significant correlation between BDNF levels and mood disorder severity in our study is consistent with findings that associate reduced BDNF with more severe depressive symptoms." (PMID 39493096, 2024). "The cross-sectional design limits causal inference, preventing us from definitively determining whether changes in BDNF and serotonin levels are the causes or effects of mood disorders." (PMID 39493096, 2024). "BDNF gene interacts with other genetic regions modulating the levels of neurotransmitters (e.g., serotonin-transporter-linked promoter region and dopamine transporter gene) in the pathogenesis of mood disorders." (PMID 36833279, 2023). "Other studies linked BDNF serum levels with mood disorders and eating disorders." (PMID 37887089, 2023). "In addition, in the mouse hippocampus, early exposure to BPA caused alterations in the expression levels of the brain-derived neurotrophic factor (BDNF) gene, which is implicated in neuronal survival, stress response, and the onset of mood disorders." (PMID 36551846, 2022). "Overall, we demonstrate that blood IL-6, GDNF and BDNF could be informative peripheral biomarkers of brain biology associated with mood disorders, substance disorders, and suicide." (PMID 34078872, 2021). "Indeed, the alteration of the normal BDNF level is strongly linked with mood disorder manifestation." (PMID 32560413, 2020). "Our findings on reduced BDNF levels in AUD and mood disorders are in line with our hypothesis and several human studies indicating that both disorders are associated with decreased levels of BDNF." (PMID 32372985, 2020). "In another study, we observed that the C-allele of a repressor region (rs12273363), associated with mood disorders, modulated the activity of BDNF promoter 4 in an allele-specific manner following cell depolarization or the combined activity of PKA and PKC pathways." (PMID 33113946, 2020). "Despite data on the cerebral BDNF level in a specific region of the brain in preclinical models, no direct evidence indicates a causal relationship between BDNF, the induction of adult neurogenesis, and mood disorders." (PMID 31118969, 2019). "In addition to conventional pathway analysis, we further considered proteins that interact with BDNF (I-Genes) and identified several biological pathways involved with BDNF or I-Genes to be significantly associated with mood disorders." (PMID 26091093, 2015).
mood disorder (continued). "Second, we reviewed curated evidence from a systematic review and meta-analysis of different study designs to evaluate the associations between BDNF and mood disorders, as well as evidence from basic experimental designs for the roles of pro-BDNF in emotion related traits." (PMID 26091093, 2015). "The neurotrophic hypothesis postulates that mood disorders such as bipolar disorder (BD) are associated with a lower expression of brain-derived neurotrophic factor (BDNF)." (PMID 26621529, 2015). "Studying these enriched pathways in future work might facilitate our understanding of the underlying etiology of mood disorders and how BDNF and its interacting molecules function to influence the risk of mood disorders." (PMID 26091093, 2015). "Systematically examining the features and biological pathways of BDNF may provide opportunities to deepen our understanding of the mechanisms underlying mood disorders." (PMID 26091093, 2015). "In past decades, various study approaches have been undertaken to explore the functions and associations of BDNF with mood disorders, such as assessing gene expression or the serum BDNF level, conducting linkage studies, or conducting individual and genome-wide association (GWA) studies." (PMID 26091093, 2015). "The BDNF Val66Met polymorphism (rs6265) might be implicated in both chronic pain conditions and mood disorders." (PMID 25383981, 2014). "BDNF has also been implicated in stress-related mood disorders." (PMID 25383981, 2014). "The striatal BDNF/TrkB system is implicated in physiologic and pathophysiologic processes, e.g. mood disorders and addiction, which present as primary diseases and as disorders associated with neurodegenerative diseases, including Alzheimer’s, Huntington’s and Parkinson’s disease." (PMID 24369067, 2013). "By increasing BDNF expression, rapamycin may support neuronal growth and synaptic connectivity, helping to reverse the structural and functional brain changes associated with mood disorders." (PMID 40589649, 2025). "Understanding the nuanced interactions between BDNF and environmental stressors may provide valuable insights into the pathophysiology of stress-related mood disorders, particularly associated with AN, and inform the development of targeted therapeutic interventions." (PMID 39203753, 2024). "Moreover, disruptions in the physiological stimulation by BDNF (like in the case of the relatively common gene polymorphism V66M) have been also shown to cause susceptibility to mood disorders, and are associated with smaller hippocampal volumes and cognitive impairment." (PMID 38645426, 2024). "Given the importance of BDNF-TrkB signalling in mediating physiological functions, including cell survival and synaptic plasticity, alterations in BDNF-TrkB signaling could be implicated in the pathophysiology of mood disorders in humans." (PMID 39042346, 2024). "In two independent samples of healthy participants, we investigated the effects of the BDNF Val66Met polymorphism on measures of excitatory neurotransmission in relation to neuronal integrity in the pgACC, a region of key importance in the pathophysiology of mood disorders such as MDD." (PMID 33762638, 2021). "Based on this study, they concluded that low BDNF levels in healthy subjects with depressive personality traits may be a risk marker, reflecting the personality profile that is associated with susceptibility to mood disorders." (PMID 33804468, 2021). "The molecular mechanisms underlying such regulations may rely upon long-term changes in stress-responsive effectors such as Brain-Derived Neurotrophic Factor (BDNF) that can affect neuronal plasticity underlying mood disorders and may also play a role in metabolic regulation." (PMID 28706476, 2017). "Furthermore, serum BDNF levels have been associated with neuronal integrity in healthy subjects and decreased BDNF peripheral levels (i.e. serum or plasma) have been consistently found in patients with mood disorders." (PMID 24593295, 2014).
mood disorder (continued). "According to the neurotrophic model for stress-related mood disorders, Met/Met homozygotes may exhibit a deficient expression of BDNF in the mood control areas of the brain during stress (e.g., chronic pain), which may predispose vulnerable subjects to mood disorders." (PMID 25383981, 2014). "Brain‐Derived Neurotrophic Factor (BDNF) rs6265 variant has been linked to emotional regulation and vulnerability to mood disorders and FM." (PMID 41460692, 2026). "Chronic stress reduces the expression of BDNF, which has an important function in both the pathophysiology of the stress response and the pathogenesis of stress-related mood disorders." (PMID 40281288, 2025). "This review gives a comprehensive synthesis of randomized controlled trials exploring the impact of green tea on mood disorder symptomology and BDNF." (PMID 40722728, 2025). "In particular, the dysregulation of neurotrophic factors, including Brain-Derived Neurotrophic Factor (BDNF), is a critical link between intermittent hypoxia and mood disorders." (PMID 39997651, 2025). "This influence contributes to the pathogenesis of several mood disorders through diverse mechanisms, including modulation of brain-derived neurotrophic factor (BDNF) and other intricate signaling pathways." (PMID 40725146, 2025). "Future studies should focus on understanding the interactions between uPA/tPA and other signaling pathways, such as BDNF and inflammatory cascades, to develop more effective treatments for mood disorders." (PMID 40725146, 2025). "Recent studies have identified genetic variants linked to both mood disorders and cardiometabolic conditions, including CACNA1D, FTO, BDNF, POMC, IGF." (PMID 39834212, 2025). "Brain‐derived neurotrophic factor (BDNF) plays an important role in the pathophysiology of stress‐related mood disorders." (PMID 39829139, 2025). "In mood disorders, dysregulated BDNF-TrkB signaling is observed, contributing to synaptic dysfunction and neuronal atrophy." (PMID 40244068, 2025). "This study aimed to assess current evidence from published randomized controlled trials testing the effects of green tea, green tea extracts, or its bioactive compounds on mood disorder symptomology and brain-derived neurotrophic factor (BDNF)." (PMID 40722728, 2025). "Althoughdecreased brain derived neurotrophic factor (BDNF) levels are believed to berelated to mood disorders and symptom severity, increased MR expression anda trend toward increased BDNF expression." (PMID 40926811, 2025). "Two of the most important substrates of music therapy in altering neuronal plasticity and alleviating mood disorders are dopaminergic signalling and brain-derived neurotrophic factor (BDNF)." (PMID 39220936, 2024). "The analysis of serum levels of BDNF and serotonin reveals differential correlations with mood disorder severity when measured by both the HAM-D and the YMRS." (PMID 39493096, 2024). "BDNF levels naturally decline with age, potentially increasing vulnerability to mood disorders in older individuals." (PMID 39493096, 2024). "The consistent effect of GC-mediated alterations on BDNF expression and the concurrence of increased circulating GC levels and low BDNF in different mood disorders, foreshadows a direct transcriptomic regulatory mechanism." (PMID 38645426, 2024). "The observed reduction in BDNF levels aligns with previous research indicating that decreased BDNF is a characteristic feature of mood disorders." (PMID 39493096, 2024). "One possible reason for the reduced white matter integrity found in individuals with social jet-lag, mood disorders, and sleep issues through alterations in Brain-derived Neurotrophic Factor (BDNF)." (PMID 39145296, 2024). "This study aims to address this gap by examining the interaction between BDNF and serotonin within the context of mood disorders." (PMID 39493096, 2024).
mood disorder (continued). "This study clarifies the prominent role of BDNF in mood disorders, as the data demonstrate reduced BDNF levels in persons with MDD and BD in comparison to healthy controls." (PMID 39493096, 2024). "Future research should explore the complex roles of both BDNF and serotonin in mood disorders to develop more targeted and effective treatments." (PMID 39493096, 2024). "This study provides critical insights into the roles of BDNF and serotonin in mood disorders, specifically MDD and BD." (PMID 39493096, 2024). "The objective was to examine the interaction between BDNF and serotonin in mood disorders, assessing their levels and correlation with disease severity and symptoms." (PMID 39493096, 2024). "The survival of neurons in this area is under the influence of BDNF, which also plays a role in the pathophysiology of mood disorders and in the mechanism of action of therapeutic agents." (PMID 39063255, 2024). "This study uniquely addresses this gap by examining how BDNF and serotonin interact and relate to mood disorder severity, providing new insights into their joint role in MDD and BD." (PMID 39493096, 2024). "BDNF, a neurotrophin crucial for the growth, upkeep, and adaptability of neurons, has been intensively studied in relation to mood disorders." (PMID 39493096, 2024). "Studies have shown that reduced BDNF levels can lead to mood disorders, which are observed in intestinal dysbiosis, characterized by an imbalance in the composition and quantity of the intestinal microbiota." (PMID 39275207, 2024). "Despite several studies, the specific mechanisms by which BDNF and serotonin interact to influence mood disorders remain incompletely understood." (PMID 39493096, 2024). "In individuals with mood disorders, notably, BDNF levels are significantly reduced, while antidepressants can increase BDNF expression and signaling." (PMID 39734634, 2024). "Specifically, genes, such as NR3C1, SLC6A4, BDNF, FKBP5, SKA2, and OXTR, exhibit alterations in DNA methylation patterns that are frequently linked to mood disorders." (PMID 38792892, 2024). "Taken together, these data strongly suggest that, at least in the hippocampus, uPA is a key player in stress-elicited mood disorders, most probably via a pro-BDNF maturation-related mechanism." (PMID 39766310, 2024). "This study contributes uniquely to understanding the combined effects of BDNF and serotonin in mood disorders by examining their levels and correlations with disease severity." (PMID 39493096, 2024). "There are studies stating that increases in BDNF serum level has stress-reducing, antidepressant effects and development of mood disorders, but the relationship between dental anxiety and BDNF has not been described in the literature." (PMID 38907644, 2024). "Many studies have confirmed the strong relationship between BDNF and mood disorders in general and BD in particular [reviewed in Lin and Huang, (2020)]." (PMID 37592949, 2023). "Similar to its role in COPD, the irisin-BDNF signaling pathway contributes to attenuation of mood disorders, including anxiety and depression, in asthma patients." (PMID 38143500, 2023). "To conclude, nutraceuticals exert an influence on factors that hold the potential to influence the initiation of mood disorders, encompassing concentrations of monoamines and BDNF, neuroinflammation, oxidative stress, and the quality of sleep." (PMID 37759862, 2023). "BDNF promotes the survival of neurons, increases synaptic plasticity and neurogenesis, regulates mood disorders, and alleviates depressive symptoms." (PMID 36982280, 2023). "The following sections deal mostly with BDNF, its role in memory-related processes and in mood disorders." (PMID 37470055, 2023). "Preclinical and clinical studies have reported that impaired BDNF signaling through its receptor TrkB in the pathophysiology of mood disorders (Castrén and Monteggia, 2021)." (PMID 38094892, 2023).
mood disorder (continued). "Due to the important role played by BDNF in the nervous system, this SNP has been extensively studied in the pathogenesis of several psychiatric disorders, including mood disorders." (PMID 37626577, 2023). "GM is also involved in synthesizing monoaminergic neurotransmitters and BDNF, which are presumed to be involved in the pathogenesis of mood disorders." (PMID 36911130, 2023). "The BDNF and serotonin systems interact with each other to regulate the development and plasticity of neural circuits involved in mood disorders, including antidepressant responses." (PMID 37242280, 2023). "It has also been indicated that BDNF regulates exercise-induced dopamine release, underpinning the effects of exercise in dopamine-related mood disorders." (PMID 37533986, 2023). "It is well known that alterations in hippocampal homeostasis, such as neuroinflammation, oxidative stress, and imbalance in neurotransmitter and BDNF levels, are crucial to the progression of mood disorders during diabetes." (PMID 37892186, 2023). "Post-mortem sampling of brain tissue, CSF, and plasma from individuals with mood disorders and substance or alcohol abuse disorders indicated a significant positive correlation between BDNF in the brain and CSF, and between BDNF in the brain and plasma." (PMID 37174977, 2023). "Various human and animal studies link BDNF and neurological conditions including, Alzheimer’s disease, mood disorders, schizophrenia, and Parkinson’s disease." (PMID 37490224, 2023). "Ketamine impaired the offspring's postnatal neurogenesis when administered in G14.5 pregnancy and it also led to neuronal apoptosis, cognitive dysfunction and mood disorder via the BDNF/CREB pathway and neurotoxic effect through Wnt/β-catenin pathway." (PMID 37119312, 2023). "Decreased levels of BDNF have been found in the hippocampus of both humans and mice exposed to mood disorders, and treatment with several antidepressants prevented the downregulation of BDNF." (PMID 35572711, 2022). "One of the most thoroughly investigated biomarkers in mood disorders is the brain-derived neurotrophic factor (BDNF)." (PMID 35448545, 2022). "Studies have generally demonstrated downregulation of BDNF gene expression in patients with SCZ and mood disorders, while increased BDNF serum levels have been reported in ASD children and ADHD boys." (PMID 35835742, 2022). "One of the most frequently studied biomarkers is brain-derived neurotrophic factor (BDNF), also a candidate biomarker for staging and treatment responses in several psychiatric disorders, especially mood disorders and suicide." (PMID 36009076, 2022). "We show the brain level of GDNF is higher for the subjects with a mood disorder compared to the control group and brain BDNF is higher in the treated groups." (PMID 34078872, 2021). "Meta-analyses of BDNF studies in adult patients with MDD or BD confirmed a significant reduction in peripheral BDNF levels in mood disorders." (PMID 34575175, 2021). "Modulation of BDNF IV levels in the ventral hippocampus showed to have a positive effect on mood disorder-related symptoms." (PMID 34068707, 2021). "It has been widely shown that serum BDNF availability correlates with mood changes and reflects the pathophysiological state in mood disorders, as well as with structural changes in specific brain regions, such as the hippocampus and cortical areas." (PMID 34298958, 2021). "Results obtained in different studies concerning the BDNF level in adolescents with mood disorders are inconsistent." (PMID 34575175, 2021). "BDNF gained attention in the study of mood disorders because data from post mortem brain tissues or serum of depressive patients indicated low levels of BDNF, which were normalized following antidepressant treatment." (PMID 34068707, 2021). "Growing evidence implicated neurotrophic factors, such as brain-derived neurotrophic factor (BDNF), played an important in the pathophysiology of mood disorders." (PMID 33850645, 2021).